LRP1 (LDL receptor related protein 1)
Diseases named in the same sentence as LRP1 in open-access papers (continued):
Sharing a sentence is not in itself a finding about the gene and the disease.
osteosarcoma (continued). "In the high TELscore group, LRP1, ITGB1, IBSP, COL1A1, and COL1A2 were the most active signaling pathways of others in osteosarcoma cells." (PMID 39980969, 2024). "The LRP1–SNRNP25, LRP1, SNRNP25, or empty vector was transfected into osteosarcoma cells with Lipo3000, and the cells were cultured for 48 h." (PMID 38678020, 2024). "Collectively, these findings indicate that the LRP1–SNRNP25 fusion gene promotes the invasion and migration of osteosarcoma cells through the pJNK/37LRP/MMP2 signaling pathway." (PMID 38678020, 2024). "In vivo, LRP1–SNRNP25 promoted the growth of osteosarcoma cells, and the pJNK inhibitor SP600125 significantly inhibited tumor growth induced by LRP1–SNRNP25 overexpression." (PMID 38678020, 2024). "First, we constructed SAOS2 and 143B osteosarcoma cell lines that stably overexpressed LRP1–SNRNP25, LRP1, SNRNP25, or the corresponding empty vector." (PMID 38678020, 2024). "Our in vitro results showed that the fusion gene LRP1–SNRNP25 promotes the invasion and migration of osteosarcoma cells by increasing the pJNK/37-kDa laminin receptor precursor (37LRP)/MMP2 protein levels." (PMID 38678020, 2024). "Recently, a novel fusion gene, LRP1-SNRNP25, was identified in human osteosarcoma by transcriptome sequencing, reverse transcription-polymerase chain reaction, and Sanger sequencing." (PMID 26738504, 2016). "Transfection of the LRP1-SNRNP25 and KCNMB4-CCND3 fusion genes into human osteosarcoma SAOS-2 cells resulted in detectable expression of fusion proteins." (PMID 25300797, 2014). "Taken together, these data suggest that LRP1-SNRNP25 and KCNMB4-CCND3 fusions confer an oncogenic effect in human osteosarcoma by enhancing cancer cell motility." (PMID 25300797, 2014). "The FISH also revealed amplification of both LRP1 and SNRNP25, suggesting a complex genetic alteration of osteosarcoma." (PMID 25300797, 2014). "In vivo, LRP1–SNRNP25 can promote the growth and metastasis of osteosarcoma." (PMID 38678020, 2024). "Third, the effect of the MMP2 inhibitor marimastat on the invasion and migration of osteosarcoma cells in mice injected with LRP1–SNRNP25-overexpressing osteosarcoma cells was not evaluated." (PMID 38678020, 2024). "In our in vitro cell experiments, we found that LRP1–SNRNP25 promotes the invasion and migration of osteosarcoma cells through the pJNK/37LRP/MMP2 signaling pathway, which can be inhibited by treatment with the pJNK inhibitor SP600125 or the MMP2 inhibitor marimastat." (PMID 38678020, 2024). "Furthermore, preliminary functional studies show that expression of LRP1-SNRNP25 and KCNMB4-CCND3 fusion genes promotes SAOS-2 osteosarcoma cell migration, while LRP1-SNRNP25 expression also promotes invasion." (PMID 25300797, 2014). "Expression of LRP1 was assessed in two other cells lines, Hepg2 (hepatocarcinoma) and MG63 (osteosarcoma), to examine whether this phenomenon is generalised in other cancer cells." (PMID 22027709, 2011). "However, the mechanism by which LRP1–SNRNP25 promotes the invasion and migration of osteosarcoma cells remains unclear." (PMID 38678020, 2024). "In the present study, considering that LRP1–SNRNP25 promoted the proliferation and metastasis of osteosarcoma cells, we further found by evaluating the signaling pathways related to the invasion and migration of osteosarcoma cells that the protein levels of pJNK and MMP2 were increased." (PMID 38678020, 2024). "In our previous study, we successfully identified and reported a new fusion gene, LRP1–SNRNP25, through whole-transcriptome sequencing of samples from 11 untreated osteosarcoma patients and verified its role in promoting the invasion of SAOS2 osteosarcoma cells in vitro." (PMID 38678020, 2024). "The rate of pJNK positivity in osteosarcoma cells with high LRP1–SNRNP25 expression was significantly higher than that in the corresponding control cells (80% vs. 40%), and MMP2 expression was also higher in cells with high LRP1–SNRNP25 expression (100% vs. 30%)." (PMID 38678020, 2024).
osteosarcoma (continued). "Furthermore, a novel fusion gene, LRP1-SNRNP25, promotes osteosarcoma cell invasion and migration." (PMID 26738504, 2016). "Since LRP1 and CCND3 play important roles in regulating tumor cell migration, invasion, proliferation and apoptosis in other cancers, we set out to test whether the chimeric proteins might play any role in osteosarcoma cells." (PMID 25300797, 2014).
Senile plaques (9 papers, 2010 to 2024). Senile plaques are extracellular deposits of amyloid in the gray matter of the brain. "In addition, LRP1 signaling pathways have been functionally implicated in AD since LRP1 has been found to be associated with senile plaques in AD brains along with the LRP1 ligands ApoE, α-2 macroglobulin and APP, which themselves are genetically and functionally associated with AD." (PMID 20205790, 2010). "Apolipoprotein E (ApoE), the ligand of LRP1, is involved in senile plaques in AD brains, implicating a role for LRP1 in the accumulation of Aβ." (PMID 35359573, 2022). "In AD patients, LRP1 was found to be up-regulated in a cell-type-dependent manner, which was manifested in the increased expression of LRP1 in neurons and astrocytes activated around senile plaques." (PMID 34349624, 2021). "Western blot demonstrated that both RAGE and LRP1 were present at higher concentrations in AD hippocampi compared with controls, with the latter possibly due to LRP1 co-localization with senile plaques." (PMID 31083442, 2019). "In EA group, the senile plaques were relatively reduced, and there were only some diffuse plaques, while the expression of LRP1 was more than that of model group." (PMID 27829865, 2016). "In fact, the soluble form of LRP1 is also likely a prominent component of senile plaques and has been found to co-localize exclusively with these ligands." (PMID 24904407, 2014). "LRP1 and its ligands have also been identified in senile plaques." (PMID 34349624, 2021). "Therefore, aging or vascular damage may impair Aβ clearance by reducing LRP1 expression in the cerebrovascular system, which leads to eventual Aβ accumulation and aggregation as senile plaques and CAA." (PMID 24904407, 2014). "Although it is not clear whether LRP1 and its ligands are independently associated with senile plaques, these observations suggest that they do interact with Aβ in AD brains." (PMID 24904407, 2014). "The importance of LRP-1 has also been shown by genetic linkage of LRP-1 with AD, and by the co-localization of LRP-1 with Aβ in senile plaques." (PMID 31139139, 2019). "Immunohistochemical analysis has revealed that LRP1 is up-regulated in neurons and in GFAP-positive activated astrocytes, in particular in astrocytic processes surrounding senile plaques in AD." (PMID 24904407, 2014).
abdominal aortic aneurysm (8 papers, 2013 to 2025). Enlargement and ballooning of the vessel that supplies arterial blood to the abdomen, pelvis and legs. "In this regard, association between human LRP1 polymorphism and abdominal aortic aneurysm, another vascular disease associated with Marfan syndrome and aberrant TGFβ signaling, has already been noted in the literature." (PMID 24312398, 2013). "Moreover, data from the literature also reported LRP1 locus contribution in abdominal aortic aneurysm susceptibility." (PMID 41515599, 2025). "Moreover, platelet-derived growth factor (PDGF)-BB, a stimulator of vascular smooth muscle cells (VSMC), proliferation, is found to be regulated by the endocytic regulator LRP1 (low density lipoprotein receptor-related protein 1), which is associated with abdominal aortic aneurysm (AAA)." (PMID 39821606, 2025). "In the same LRP1 gene, another SNV rs1466535 located in an adjacent haplotype block to rs11172113 was associated with an increased risk of abdominal aortic aneurysm formation." (PMID 35050224, 2022). "PHACTR1 and LRP1 were also associated with cervical artery dissection and spontaneous coronary artery dissection, and LRPI was additionally associated with abdominal aortic aneurysm 23–25." (PMID 34654805, 2021). "Literature data indicated that MMP-9 clearance depends on the expression of low-density lipoprotein receptor-1 (LRP1) -bound protein, therefore, LPR1 is considered an important element in the pathogenesis of abdominal aortic aneurysm." (PMID 35745168, 2022). "Interestingly, aortic, but not plasma, concentrations of soluble forms of LRP1 were significantly lower in patients with abdominal aortic aneurysm (AAA) compared with controls." (PMID 36472907, 2023).
cognitive decline (8 papers, 2010 to 2026). "In AD patients and elderly people, brain LRP1 level decreases significantly, and has an inverse relationship with the age of AD onset, which indicates that reduced LRP1 function causes cognitive decline." (PMID 39906286, 2025). "We demonstrated that VMC-specific LRP1 KO leads to VCID-related phenotypes such as cognitive decline and BBB dysregulation in middle-aged mice with APOE4, while the deletion did not induce evident phenotypes in APOE3 carriers." (PMID 37036005, 2023). "In addition to epidemiological studies based on VD3 intake, genetic research has also shown a connection between polymorphisms in the VDR or low-density lipoprotein receptor-related protein 1 (LRP1) genes and risks of cognitive decline or AD." (PMID 39063051, 2024). "In AD patients and in elderly people, brain LRP1 levels are significantly decreased and inversely correlate to the age of onset of AD, suggesting that a decrease in LRP1 function might contribute to the cognitive decline." (PMID 20686698, 2010). "Therefore, indomethacin improved cognitive decline in APP/PS1 Tg mice by suppressing the production and deposition of Aβ and inducing Aβ efflux through a mechanism mediated by A2M-induced LRP1 activation." (PMID 34360951, 2021).
endometrial carcinoma (8 papers, 2016 to 2025). A malignant tumor arising from the epithelium that lines the cavity of the uterine body. "Aberrant overexpression of LRP1 has been observed in the malignancy and driven progression in pancreatic, breast, and endometrial cancers." (PMID 40625660, 2025). "LRP1 is reported to be upregulated in endometrial carcinomas, malignant glioma, triple negative breast cancer and is linked with tumor metastasis and poor prognosis." (PMID 37020553, 2023). "In addition, low expression of LRP1 was reported in human endometrial carcinoma, prostate cancers, lung cancer, and Wilm’s tumors." (PMID 37020553, 2023). "In addition, increasing levels of LRP1 expression is commonly observed in the majority of endometrial carcinomas, suggesting that LRP1 is involved in the formation of endometrial carcinoma." (PMID 26738504, 2016).
gallbladder cancer (8 papers, 2022 to 2025). "In ErbB pathway-mutated gallbladder cancer, upregulation of secreted midkine facilitates differentiation of immunosuppressive macrophages through biding with its receptor LRP1." (PMID 36906597, 2023). "Increased MDK in tumour cells promoted immunosuppressive differentiation of tumour‐infiltrating macrophages by an interaction with its receptor LRP1 in ErbB pathway‐mutated gallbladder cancer." (PMID 35678121, 2022). "Interestingly, a study has shown that MDK is upregulated in gall bladder cancer with ErbB pathway mutations and promotes the differentiation of immunosuppressive macrophages by interacting with LRP1 on TAM60." (PMID 40894019, 2025). "In their gallbladder cancer research, MDK interacts with its receptor LRP1, which is expressed by tumor-infiltrating macrophages, and further promotes immunosuppressive macrophage differentiation." (PMID 35558067, 2022). "Similarly, in gallbladder cancer, upregulation of MDK enhances its interaction with LRP1—expressed by tumor-infiltrating macrophages—promoting the differentiation of immunosuppressive macrophages." (PMID 41246334, 2025).
multiple sclerosis (8 papers, 2015 to 2023). A progressive autoimmune disorder affecting the central nervous system resulting in demyelination. "Previous study indicated that direct protein-protein binding effects of apoE with its signal receptor LRP1 enable microglia to exert immunosuppressive and neuroprotective effects in neuroinflammation caused by hemorrhagic stroke, traumatic brain injury, and multiple sclerosis." (PMID 36035210, 2022). "The products of C3 and Lrp1 were also shown to play a role in pathogenesis of multiple sclerosis or EAE and the product of Nrp2 is involved in the remyelinating process in demyelinating lesions." (PMID 36817487, 2023). "Non-cell-autonomous functions for LRP1 following white matter lesion are likely, since LRP1 is upregulated in astrocytes and myeloid cells near multiple sclerosis lesions." (PMID 29251594, 2017). "Supporting its central role in Multiple sclerosis pathology, we find that LRP1 expression is increased in Multiple sclerosis lesions in comparison to the surrounding healthy tissue." (PMID 27400748, 2016). "LRP1 protein expression was substantially increased in the cerebellum and in the spinal cord after experimental autoimmune encephalomyelitis in mouse, an experimental model of multiple sclerosis, suggesting that LRP1 is major receptor for phagocytosis of degraded myelin." (PMID 31080804, 2019). "Taken together, our data suggest that the function of LRP1 in microglia is to keep these cells in an anti-inflammatory and neuroprotective status during inflammatory insult, including experimental autoimmune encephalomyelitis and potentially in Multiple sclerosis." (PMID 27400748, 2016). "Furthermore, LRP1 has also been hypothesized to play a crucial role in clearing apoptotic cells during multiple sclerosis." (PMID 26031516, 2015). "Here, we explore the myeloid cell function of Low-density lipoprotein receptor-related protein-1 (LRP1), a scavenger receptor involved in myelin clearance and the inflammatory response, in the context of Multiple sclerosis." (PMID 27400748, 2016). "Of note, their work also suggests that ablation of LRP1 in microglia, not in macrophage, had a significant impact on the disease severity of multiple sclerosis." (PMID 27931217, 2016). "Using two genetic mouse models, we show that deletion of LRP1 in microglia, but not in peripheral macrophages, negatively impacts the progression of experimental autoimmune encephalomyelitis, an animal model of Multiple sclerosis." (PMID 27400748, 2016).
viral infections (8 papers, 2012 to 2026). "The fact that EMCV infection is unabated at all time points demonstrates that LRP1-deficient cells are in principle still able to support virus infection." (PMID 37072184, 2023). "Expression of SFTSV receptors C‐C motif chemokine receptor 2 (CCR2) and lipoprotein receptor‐related protein 1 (LRP1) in pancreatic organoids supported viral infection." (PMID 41090515, 2026). "Experimental models indicate that LRP1 is a potential defense mechanism in acute viral infections and related organ injuries." (PMID 37168200, 2023). "Our findings not only confirmed the crosstalk between LRP1 and Notch signaling pathway, but also provided new insights into Notch signaling upon virus infections." (PMID 37743411, 2023). "We confirmed that LRP-1 protein expression is reduced during infection, and during stimuli that occur during virus infection such as exposure to reactive oxygen species and changes in cholesterol concentration." (PMID 31015516, 2019). "LRP1 is a regulator of cholesterol homeostasis, and cholesterol is important for virus infection." (PMID 37072184, 2023). "The previous studies indicated that LRP1 could be a defense mechanism against acute viral infections." (PMID 35997994, 2022). "Our data suggest that multiple stimuli that are present during virus infection can reduce LRP-1 protein expression and that this may be due to RIP." (PMID 31015516, 2019). "On the other hand, the fact that other viruses that constitute a concern to public health interact with LRP1 for infection makes this receptor an interesting target for the development of antiviral drugs with the potential to be effective in the treatment of various viral infections." (PMID 39599807, 2024). "Viral infection reduces LRP-1 protein expression, and dsRNA knockdown of LRP1 increases intracellular cholesterol and DenV viral RNA." (PMID 37168200, 2023). "Furthermore, enhanced surface CD91/LRP-1 expression could be detected as early as 8 hours following HIV-1 infection, suggesting that the mechanisms involved were happening early in the virus infection process." (PMID 22412921, 2012). "Thus, the phenotype of LRP1 deficiency under RVFV infection is measurable, but appears to be weaker in human cell lines than in mESCs, possibly because ESCs are in general more prone to virus infection because of their lack of an antiviral interferon system." (PMID 37072184, 2023).
astrocytoma (7 papers, 2016 to 2025). "Among the reported LRP1 mutations are the polymorphic alleles of C766T in exon 3 of the gene that was reported several decades ago in astrocytoma." (PMID 32245111, 2020). "On immunohistochemistry, LRP-1 expression was present in all astrocytomas, with the majority of the GBMs showing high expression and was negative in the normal brain." (PMID 36267880, 2022). "On the other hand, high LRP1 expression was reported in the advanced tumor stage of astrocytoma, endometrial, and breast cancer, further suggesting conflicting roles of this gene, which warrant future research." (PMID 32245111, 2020). "It was demonstrated previously that the interaction of it with the lipoprotein receptor-related protein-1(LRP1) of low-density led to an inhibition of tumour cell proliferation, migration, and invasion in astrocytoma malignancy." (PMID 31186631, 2019). "Recently, we investigated the impact of A2M and LRP1 on cellular properties of 1321N1 astrocytoma cells." (PMID 29281661, 2017). "Moreover, the same study also reported that LRP1 gene amplification in occurrence with EGFR amplification was observed in high-grade astrocytomas (Grade IV), compared to normal brain tissues." (PMID 32245111, 2020). "In addition, LRP1 gene amplification has been found in astrocytoma, with 68 % of high-grade astrocytomas (grade IV) exhibiting high expression of LRP1, compared with the lack of LRP1 expression observed in 91 % of normal brain tissues." (PMID 26738504, 2016). "Moreover, compared with low-grade astrocytoma, malignant glioma has been characterized with significantly higher levels of LRP1 mRNA and protein." (PMID 26738504, 2016). "Similar to the present study, the expression of LRP-1 was significantly higher in GBM, IDH wild type as compared to astrocytomas, IDH mutant, grade 4 (p-value- 0.004)." (PMID 36267880, 2022). "Notably, GBM cases exhibit significantly LRP1 higher expression than low‐grade astrocytoma (LGA) and high‐grade astrocytoma (HGA) cases, suggesting a correlation between LRP1 expression and the poor outcome of the tumors." (PMID 39276062, 2024). "The LRP-1 and ABCA-1 mRNA expression of the GBM cases was significantly higher than the normal brain/non-tumor tissue and lower-grade astrocytomas." (PMID 36267880, 2022).